ALB (albumin)
Diseases named in the same sentence as ALB in open-access papers (continued):
Sharing a sentence is not in itself a finding about the gene and the disease.
Hypoalbuminemia (continued). "Univariate logistic regression analyses showed that HCV, HD duration, Kt/Vurea (Daugirdas), normalized catabolic rate (nPCR), Hb level, hypoalbuminemia (albumin <4 g/dL), log iPTH level, and BLLs were positively associated with CTS." (PMID 31498017, 2019). "After matching, both overall complication (B = 0.064, p < 0.001) and length of total hospital stay (B = 2.236, p < 0.001) were still greater in the mild hypoalbuminemia group than in the group with normal serum albumin levels." (PMID 31253199, 2019). "In this study, although the mean serum albumin was normal and identical before and after ZS after ZS, there was a slight increase in hypoalbuminemia cases from 36.8% to 37.5%, and two children had hypozincemia and hypoalbuminemia at the same time." (PMID 31694220, 2019). "Serum albumin is considered as a clinical monitoring tool for nutrition assessment, and hypoalbuminemia is strongly correlated with the complications and mortality in the elderly." (PMID 30651062, 2019). "Patients with hypoalbuminemia (<35g/L) scored 73.7 ± 12.3, and with normal albumin scored 68.0 ± 13.7; the difference between groups was significant (P = 0.02)." (PMID 31456321, 2019). "Shorter overall survival (OS) was observed in patients with hypoalbuminemia (5-year OS rate 17.1%) when compared to patients with normal serum albumin levels (5-year OS rate 58.6%, p = 0.004)." (PMID 31468203, 2019). "Kaplan–Meier analysis revealed that the survival rate of patients with hypoalbuminemia was significantly lower than in those with serum albumin levels at or above 3.5 g/dL (p < 0.001)." (PMID 31565439, 2019). "We determined the influence of hypoalbuminemia (albumin≤3.5 g/dL) and normoalbuminemia (albumin>3.5 g/dL) on the bone formation and resorption markers in different PTH groups." (PMID 31839746, 2019). "In comparison with patients who have normal serum ALB, patients with hypoalbuminemia have a higher rate of sepsis." (PMID 30918528, 2019). "In acute hypoalbuminemia, we can consider two cases of albumin depletion or addition, based on the electroneutrality assumption." (PMID 30196793, 2018). "In contrast to previously published data, addressing the factor albumin as the weak point in mGPS, we found, that preNT-hypoalbuminemia is an independent prognostic factor." (PMID 29467943, 2018). "Protein imbalance is represented by the increase of total serum proteins (hyperproteinemia), hyperglobulinemia, and hypoalbuminemia, which also determines the inversion in the albumin/globulin ratio." (PMID 29789784, 2018). "In patients undergoing dialysis, it is unclear whether hypoalbuminemia is simply secondary to poor nutrition itself or is associated with other complex conditions such as chronic systemic inflammation, fluid overload, underlying comorbidities, and impaired compensatory hepatic synthesis of albumin." (PMID 30235860, 2018). "They concluded that serum level of albumin at admission is considered as a good indicator of the functional outcome and trials for the correction of hypoalbuminemia in acute ischemic stroke would be helpful to decrease the risk of poor outcome." (PMID 30046235, 2018). "A total of 4 out of 40 dogs (10%) had serum albumin concentrations of < 20 g/L (median 12.2 g/L; range 11–13 g/L), with a hypoalbuminemia severity scores of 2 for two dogs and of 3 for another two." (PMID 29530095, 2018). "A 39.17% of patients had hypoalbuminaemia (serum albumin <35 g L−1), 89.04% of patients were anemic (HB <110 g L−1) and almost a half of patients were hypocalcaemic and hyperphosphataemic." (PMID 30343613, 2018). "Further, in the light of the observed levels of serum albumin which were found to be decreased, it is tempting to infer that NDEA induced liver fibrosis causes hypoalbuminaemia and pomegranate juice is a prominent player in restoring the levels back to normal." (PMID 29872102, 2018).
Hypoalbuminemia (continued). "Although several tCa levels were related to the mortality in hypoalbuminemia, albumin had little effect on tCa in prognostic value of mortality." (PMID 30046608, 2018). "According to the literature, suture technique, bile duct diameter, hypoalbuminemia (albumin <35 g/L) and blood supply to the bile duct seem to be important factors related to the occurrence of bile leak." (PMID 29479444, 2018). "Hypoalbuminemia has been known to be a strong independent predictor of poor outcome in adults, and the lowest serum albumin level showed significant inverse correlation in ELBWIs." (PMID 29438382, 2018). "Hypoalbuminemia means that fewer albumin molecules can bind to furosemide and that a smaller amount of furosemide is delivered to the proximal tubule, which induces diuretic resistance." (PMID 29063302, 2018). "Overall, 10% of the patients had hypoalbuminemia with concentrations of albumin below the reference range." (PMID 29324643, 2018). "In our study, 37 patients (52.9%) had hypoalbuminemia (ALB < 35 g/L) and 33 patients (47.1%) had an ALB level ≥ 35 g/L." (PMID 29506546, 2018). "While an association between hypoalbuminemia and increased risk of acute kidney injury (AKI) is well-established, the risk of AKI development and its severity among patients with elevated serum albumin is unclear." (PMID 29927987, 2018). "In addition, some cohort studies have indicated that the presence of hypoalbuminemia may also increase the risk of BPAEs from GCs, as lower levels of serum albumin would be related to higher levels of free and active GCs, which are normally inactive when bound to albumin." (PMID 30071590, 2018). "A total of 1275 (40%) of those had preoperative serum albumin levelsincluded, and 53 (4.15%) patients were classified as having preoperative hypoalbuminemia(serum albumin <3.5 g/dL)." (PMID 30443474, 2018). "Low serum albumin level (SAL) (< 35 mg/dL), or hypoalbuminemia, is a well- documented risk factor for postoperative pulmonary complications in many patient populations." (PMID 29135994, 2017). "The interplay of hypoalbuminemia, cachexia and the inflammatory response may contribute to progressive loss of vital protein in patients with hilar cholangiocarcinoma; further, the long half-life of serum albumin may provide a longitudinal assessment of the patients’ wellbeing." (PMID 27389416, 2017). "Our observations indicating a dependency of tumor growth in mouse xenografts on albumin accumulation, combined with the correlation between hypoalbuminemia and tumor size, are consistent with earlier suggestions that tumors scavenge this protein." (PMID 27974681, 2017). "A total of 110 (55%) patients had an elevated CRP concentration (10 mg/L), and 22 (11%) patients had hypoalbuminemia (albumin <35 g/L) prior to surgery." (PMID 28431566, 2017). "We imply that hypoalbuminemia is a predictor of cardiovascular morbidity and mortality due to vasculopathy mediated by oxidized modified undetected albumin." (PMID 28542419, 2017). "Colloid solutions such albumin can be used in patients with hypoalbuminemia in the setting of fluid volume deficit, hypotension, and AKI." (PMID 28932401, 2017). "Hypoalbuminemia was very prevalent among our patients, and 40.5% of them presented severe hypoalbuminemia (serum albumin < 2.5 g/dL)." (PMID 28231825, 2017). "The incidence of organ failure was 3.5%, 10.6%, and 41.6% in patients with normal albumin and mild and severe hypoalbuminaemia, respectively." (PMID 29147647, 2017). "We showed, for the first time, a mechanistic link between hypoalbuminemia and the pro-inflammatory properties of in-vivo oxidized albumin, initiating vascular injury." (PMID 28542419, 2017). "More patients had Fuhrman grade 3–4 RCC in the post-treatment hypoalbuminemia group (63.2%, 24/38) than in the post-treatment normal albumin level group (28.1%, 41/146; P < 0.001)." (PMID 28521783, 2017).
Hypoalbuminemia (continued). "In our study, we observed 74 (13.66%) patients with albumin <3.5 g/dL and hypoalbuminemia was predictor for OS and PFS in univariate analysis." (PMID 28578683, 2017). "Taking into consideration that half of circulating calcium ions are bound to albumin, this effect resulted probably from hypoalbuminemia." (PMID 28193264, 2017). "Once these in-vivo albumin modifications were reduced in- vitro, the apparent hypoalbuminemia concomitantly with its inflammatory effects, were eliminated." (PMID 28542419, 2017). "Low pre-albumin level was defined as <20 mg/dl, while hypoalbuminemia was defined as albumin <35 g/L." (PMID 27906675, 2017). "Of these, 38 patients constituted the post-treatment hypoalbuminemia (<36.4 g/L) group, and 146 patients constituted the normal post-treatment albumin level (≥36.4 g/L) group." (PMID 28521783, 2017). "In the event of oxidative stress and inflammation to which HD patients are exposed, albumin is oxidized and undetected by common laboratory methods, rendering an apparent hypoalbuminemia." (PMID 28542419, 2017). "In our study, we found that in localized UTUC, the rate of low pre-albumin level (59/425,13.9%) was much higher than that of hypoalbuminemia (17/425, 4.0%)." (PMID 27906675, 2017). "Hypoalbuminemia in VL derives from hepatic dysfunction, impaired albumin production and reduced intestinal absorption of proteins due to protein loosing enteropathy." (PMID 28231825, 2017). "In other studies, hypoalbuminemia, defined as either an albumin < 3.0 or <3.5 mg/dL, was used as a component of perioperative predictive scoring models that assess frailty and fitness to predict outcomes for pancreatic cancer and pancreatic surgery." (PMID 28272344, 2017). "Serum albumin levels decline with age, and the proportion of patients with hypoalbuminemia, nosocomial infections, commensal pneumonia, cancer and sepsis, and pressure sores has been used as risk factors for death." (PMID 31011042, 2017). "Hypoalbuminemia and nutritional supplements were the most inappropriate reasons for albumin consumptions." (PMID 28979337, 2017). "Serum albumin is considered as a clinical monitoring tool for nutritional assessment, and hypoalbuminemia is strongly correlated with complications and mortality in the elderly." (PMID 28164133, 2017). "Within the two months of the study, human albumin was used most frequently for hypoalbuminemia (33%) and plasmapheresis (30.2 %)." (PMID 28979337, 2017). "Hypoalbuminemia, defined in studies as albumin levels between 2.1 and 3.5 mg/dL, is predictive of greater postoperative complications." (PMID 28272344, 2017). "This is in contrast to other states of hypoalbuminemia, like malnutrition and liver failure, when there is a low synthesis rate of albumin." (PMID 27846908, 2016). "the prevalence of hypoalbuminemia proved to be high, in approx. nine in tenelders, and the nutritional status and the length of stay proved to be related tothe decrease of serum albumin levels." (PMID 27508908, 2016). "Diabetic nephropathy induced hypoalbuminemia has been attributed to urinary albumin excretion and occurs contrary to the great potential hepatic albumin production capacity." (PMID 27921024, 2016). "To assess the impact of albumin on different tumor stages, we divided patients into subgroups by N-stage (N0 vs. N1-4), and found hypoalbuminaemia as a worse survival factor in both N0 group (X2 = 11.078, p = 0.004) and N1-4 group (X2 = 7.236, p = 0.027)." (PMID 28003023, 2016). "Thesame happened with the serum albumin levels; approximately 66.7% (n=6) of thepatients who had hypoalbuminemia showed postoperative clinical complications;however, they had no statistical significance." (PMID 27982346, 2016).
Hypoalbuminemia (continued). "Only nephrotic range proteinuria (urinary total protein, UTP ≥ 3 g/day), severe hypoalbuminemia (serum albumin < 20 g/L) and serum albumin significantly and negatively affected attainment of remission (p < 0.05)." (PMID 27717323, 2016). "Serum albumin was dichotomized at 3.5 g/dL because any value below this is considered hypoalbuminemia." (PMID 26908009, 2016). "Since the serum albumin is an important antioxidant in the blood and extracellular environment, hypoalbuminemia contributes to the occurrence and development of oxidative stress in patients with CKD." (PMID 27127544, 2016). "A large prospective study on emergency department patients showed that the short-term mortality of patients with hypoalbuminemia was three times higher compared with patients with normal albumin after adjusting for several confounders." (PMID 27433355, 2016). "Mean serum albumin at baseline indicated hypoalbuminemia (n = 40, 3.0 ± 0.8 g/dL; range 1.4–4.0 g/dL), and significant improvement was shown post-Acthar gel therapy (n = 35; mean improvement 0.53 ± 0.6 g/dL, P < 0.0001)." (PMID 27036111, 2016). "Serum albumin is an important marker of nutritional status, and hypoalbuminemia is correlated with cachexia." (PMID 27104127, 2016). "A 50 % elevated de-novo albumin synthesis rate was seen in patients with acute inflammation and marked hypoalbuminemia, while patients with marginal hypoalbuminemia before the start of surgery had a normal albumin synthesis rate." (PMID 27846908, 2016). "All of the patients showed albumin concentrations below the reference value upon admission, and 77% maintained hypoalbuminemia on the 7th day of hospitalization." (PMID 27982165, 2016). "Specifically, with this assay, the hypoalbuminemia observed in proteinuric and HD patients results partially from impaired detection of modified/oxidized albumin molecules." (PMID 27453993, 2016). "Since COP correlates with total serum albumin even when modified or oxidized, this measure has potential benefit in developing unique assays for improved assessment of true hypoalbuminemia." (PMID 27453993, 2016). "These processes are connected with the degradation of serum albumin, which then leads to hypoalbuminemia." (PMID 26757706, 2016). "Exogenous albumin is used extensively in clinical practice, for hemodynamic stabilization and to treat hypoalbuminemia." (PMID 27846908, 2016). "This suggests that the degree of albumin leak—and thus hypoalbuminemia—is correlated with sepsis progression." (PMID 26908009, 2016). "Compared with sATT, the iATT + STM regimen was more beneficial for patients with higher serum albumin concentrations than for those with more severe hypoalbuminemia." (PMID 27231666, 2016). "Initial serum albumin level was available in 13 patients only and 11 of them (84.6%) had hypoalbuminemia (albumin < 3 g/dL)." (PMID 27938338, 2016). "In clinical states associated with systemic oxidative stress (OS) and inflammation such as chronic kidney disease (CKD), oxidative modifications of serum albumin impair its quantification, resulting in apparent hypoalbuminemia." (PMID 27453993, 2016). "Using serum albumin concentration below 3.0 grams per deciliter to define hypoalbuminemia, 151 hypoalbuminemic cases and 104 normoalbuminemic controls were enrolled." (PMID 27504458, 2016). "In the human body albumin serves as a reservoir for NO, so that hypoalbuminemia also reduces the bioavailability of NO and the endothelium-dependent vasodilatation." (PMID 27127544, 2016). "Nephrotic range proteinuria (UTP ≥ 3 g/day) and severe hypoalbuminemia (serum albumin < 20 g/L) at baseline influenced remission (p <0.05)." (PMID 27717323, 2016). "Serum albumin is commonly considered a marker of nutritional status, but the reasons for hypoalbuminemia among hospitalized patients are complex." (PMID 26908009, 2016).
Hypoalbuminemia (continued). "The prevalence of hypoalbuminemia in elders at the sixth day of hospitalization was 90%(n=110) and only 10% (n=12) had normal albumin levels, a statistically significantdifference (p=0,000) for both classifications." (PMID 27508908, 2016). "Preoperative hypoalbuminemia (serum albumin <3.5 g/dL) was observed in 75 (14.3 %) patients and preoperative anemia (hemoglobin <12.0 g/dL) in 121 (23.0 %)." (PMID 26194797, 2015). "To examine how much GI symptoms and inflammation mediated the association between lower eGFR and hypoalbuminemia, we simultaneously controlled for GI symptoms and CRP in a model with eGFR as the exposure and serum albumin as the outcome." (PMID 26651991, 2015). "Taking into account the clinical significance, we defined hypoalbuminemia as an albumin level of less than 25 g/L, thus its incidence was 70.4% (95/135) in this study, which was also consistent with the previous reports." (PMID 26557421, 2015). "Hypoalbuminemia was the only modifiable factor in our patient, and dramatic response to albumin indicates the etiology of the effusion." (PMID 26486858, 2015). "Hypoalbuminemia (serum albumin level <3.2 g/dL) was present in 3 of 20 patients (15%) and none of them had a PCF (0%) (p = 0.596, p > 0.05)." (PMID 26366434, 2015). "Biochemical parameters used with CRP (specifically in renal cell carcinoma) were: albumin (alone or as hypoalbuminemia), LDH, and interleukins (IL-6, IL-8, IL-2)." (PMID 26717416, 2015). "In a patient with hypoalbuminemia (serum albumin concentration <2 g/dL), furosemide is less bound to albumin and the free drug diffuses into the tissues with resultant increase in its volume of distribution." (PMID 26457719, 2015). "It is well established that both diuretics and albumin will induce diuresis and natriuresis in patients with edema and hypoalbuminemia." (PMID 26457719, 2015). "It has been reported that morbidity and mortality incidence of dialysed patients with hypoalbuminemia is higher than in patients with normal serum albumin." (PMID 26491522, 2015). "Our data showed that in CAG, the patients’ serum albumin levels were high, and very few patients had hypoalbuminemia." (PMID 25880463, 2015). "Although comparable diuretics were used, correction of hypoalbuminemia by administration of human albumin solutions resulted in less pronounced fluid retention." (PMID 26136776, 2015). "The combination of a loop diuretic (furosemide) and albumin has resulted in decrerased edema, particularly in patients with hypoalbuminemia." (PMID 26457719, 2015). "Because hypoalbuminemia is related to declining kidney function, blood albumin and/or urinary albumin are useful markers for assessing the preservation of renal tissue." (PMID 26090382, 2015). "In digestive tumors common biochemical parameters used were: albumin (alone or hypoalbuminemia), carcinoembryonic antigen (CEA), cancer antigen 19–9 (CA19-9) and interleukins (IL-6, IL-8, IL-2)." (PMID 26717416, 2015). "Twelve cases had hypoalbuminemia (12/17, 70.6%) and the mean serum albumin level of all 17 cases was (30.4 ± 7.5) g/L." (PMID 26090493, 2015). "Against this background, the implementation of prospective randomized controlled trials on renal protection with exogenous human albumin in patients with hypoalbuminemia seems more than justified." (PMID 26136776, 2015). "Based on this of the patients with hyperuricemia 88.5% had hypoalbuminemia while 91.7% of those with a uric acid level <7 mg/dL had a low albumin level." (PMID 26294973, 2015). "Of the 3599 participants in our study, the mean age was 58.4 ± 10.9 years, 55 % were men, the mean BMI was 32.2 ± 7.8 kg/m2, mean serum albumin was 3.95 ± 0.46 g/dL; 12.7 % had hypoalbuminemia." (PMID 26651991, 2015). "In an adult the normal range of serum albumin is defined as 3.55.0 g/dl and a level < 3.5 g/dl is called hypoalbuminemia." (PMID 26264480, 2015).